ALB (albumin)
Diseases named in the same sentence as ALB in open-access papers (continued):
Sharing a sentence is not in itself a finding about the gene and the disease.
Sepsis (continued). "Low serum albumin levels increase vascular endothelium permeability, exacerbating fluid buildup and decreasing circulatory function in sepsis." (PMID 40283655, 2025). "The objective of this study is to investigate the correlation between the combination of albumin with crystalloids and the 90-day mortality of ischemic stroke patients with sepsis." (PMID 41468394, 2025). "Our findings also suggested that male patients with bacterial infections and high procalcitonin levels, lower albumin levels, or prolonged prothrombin times were more likely to develop sepsis." (PMID 39975676, 2025). "Similar to sepsis, in ARF patients, a higher SOFA score, LAR, Lactate values, and lower albumin levels were linked to poor in-hospital outcomes requiring inotropes and mechanical ventilation." (PMID 40130722, 2025). "This study aimed to evaluate the prognostic value of the Creatinine to Albumin Ratio (CAR) in predicting 30-day mortality in patients with sepsis complicated by acute kidney injury (AKI)." (PMID 41425961, 2025). "Other laboratory indicators, such as alkaline phosphatase (ALP), C-reactive protein (CRP), albumin (ALB) and lactate (LAC), are risk factors for SRLI in patients with sepsis." (PMID 39712312, 2024). "The lactate to albumin ratio (LAR) has been associated with the severity and outcome of critical illness and sepsis." (PMID 39272772, 2024). "In the Albumin Italian Outcome Sepsis (ALBIOS) study, albumin dosing to maintain serum levels of 30 g/L enabled a lower net fluid balance and higher mean arterial pressure than did saline dosing, despite the administration of similar total fluid amounts." (PMID 39336939, 2024). "The analysis conducted on a cohort of sepsis patients revealed essential findings related to the 28-day mortality rate and survival time across different L/A ratios, albumin levels, and lactate concentrations." (PMID 38518050, 2024). "Overall, albumin serves not only as an important prognostic marker but also as a potential therapeutic target for improving the outcome of critically severe sepsis and SAE patients." (PMID 39135753, 2024). "Serum lactate, albumin, lactate/albumin ratio, C-reactive protein, platelet levels, and three sepsis severity scales, (CCI, SOFA, APACHE IV) were assessed." (PMID 38576552, 2024). "It is imperative to acknowledge that in patients with sepsis in the ICU, the fluctuations in serum albumin levels are inextricably linked to the volume of exogenous albumin administered." (PMID 39101009, 2024). "Serum albumin level is emerging as a reliable predictor of prognosis and severity of sepsis especially in resource-limited countries." (PMID 39539863, 2024). "Recently, two biomarkers have gained momentum as prognostic factors for sepsis and septic shock: lactate dehydrogenase (serum lactate), and lactate/albumin (L/A) ratio." (PMID 38576552, 2024). "We identified a critical threshold for serum albumin levels in sepsis patients at 30 g/L, below which the likelihood of mortality and acute kidney injury significantly increases." (PMID 39101009, 2024). "The blood urea nitrogen to albumin ratio (BAR) has been demonstrated as a prognostic factor in sepsis and respiratory diseases, yet its role in severe coronary heart disease (CHD) remains unexplored." (PMID 38553557, 2024). "Eight studies disclosed the useof the AUC of the lactate/albumin ratio in predictingmortality in sepsis patients according to the receiveroperating characteristic curve." (PMID 39139159, 2024). "Microcirculatory fluorescence recordings showed that the permeability of mesenteric microveins to FITC‐labeled bovine serum albumin (BSA) was significantly increased after sepsis (P < 0.05)." (PMID 39447130, 2024). "This prospective study aimed to compare the impact of albumin versus saline infusion on peripheral tissue perfusion in a selected population of patients with sepsis and persistent impaired tissue hypoperfusion despite initial resuscitation." (PMID 38326920, 2024).
Sepsis (continued). "Serum sPLA2 and albumin showed an inverse relationship with increasing sPLA2 activity and decreasing albumin membrane-binding activity in patients with evolving complications of sepsis." (PMID 39273360, 2024). "Patients with increased severity of sepsis had lower serum albumin levels in contrast to those with less severe sepsis." (PMID 39539863, 2024). "Here, we observed the probable beneficial effect of albumin on sepsis induced tissue hypoperfusion over saline." (PMID 38326920, 2024). "Our study clearly demonstrated that the differences in lactate, albumin, and the L/A ratio within 24 hours of admission between the survival and death groups of patients with sepsis were statistically significant." (PMID 38518050, 2024). "Albumin is the most commonly used colloidal fluid in the treatment of sepsis, and its use in sepsis is still highly controversial." (PMID 38229151, 2024). "The results from nomogram showed that APACHE II and albumin were also predictors of a poor prognosis in patients with ARDS induced by sepsis." (PMID 39686985, 2024). "Wang B. and colleagues were the first to demonstrate the lactate/albumin ratio as an independent predictor of mortality in patients with severe sepsis and septic shock." (PMID 39685564, 2024). "In our retrospective cohort study, four distinct serum albumin trajectory groups were identified in sepsis patients." (PMID 39101009, 2024). "Contrarily, the C-reactive protein/albumin ratio and qPitt bacteremia score are two relatively simple to use, widely available, and readily obtained severity scores in patients with sepsis." (PMID 39252713, 2024). "This inverse relationship suggests a crucial regulatory mechanism affecting cell membrane phospholipid homeostasis and albumin structural alterations in systemic inflammation in sepsis." (PMID 39273360, 2024). "Studies have shown that the LAR exhibits enhanced predictive accuracy for sepsis prognosis compared to individual assessments of lactate and albumin." (PMID 38195421, 2024). "Recent research has demonstrated the predictive value of Lactate-to-Albumin Ratio (LAR) in sepsis and septic shock." (PMID 38195421, 2024). "The comprehensiveanalysis results revealed that the lactate/albumin ratiodemonstrates a good discriminatory power to predictmortality in sepsis patients (AUC=0.75, 95% CI: 0.68to 0.84, I2=92.9%)." (PMID 39139159, 2024). "Previous studies have suggested that there is a correlation between serum albumin and the prognosis of patients with sepsis, but few studies have found a correlation between albumin and SAE." (PMID 39135753, 2024). "In instances where there is suspicion of hypoperfusion in sepsis with low blood volume, a minimum of 30 ml/kg of crystalloid solution (potentially including albumin) is advised for shock therapy." (PMID 39867932, 2024). "Our research indicates that for the majority of sepsis patients, serum albumin levels remained stable during the initial 7 days." (PMID 39101009, 2024). "Außer für spezielle Indikationen, so etwa bei Patient:innen mit Leberzirrhose oder „resuscitation“ in der Sepsis nach initialer Volumentherapie mit BK, sollte Albumin nicht eingesetzt werden." (PMID 39382683, 2024). "Participants with severely increased albuminuria (ACR > 30 mg/mmol) had HR 3.60 for BSI (95% CI 2.30–5.6) and 3.14 for sepsis (95% CI 1.94–5.1) compared to normal albumin excretion (ACR < 3 mg/mmol)." (PMID 38679665, 2024). "In our study, sepsis patients exhibited higher serum albumin and platelet levels, while those with septic shock were characterized by advanced age, a shorter length of hospitalization, more comorbidities, and higher organ failure indices and APACHE scores." (PMID 38576552, 2024). "Recognized as a marker of systemic inflammation, the prognostic capabilities of albumin for sepsis have been well-documented in numerous studies." (PMID 38518050, 2024).
Sepsis (continued). "Among sepsis patients with stable albumin levels above 30 g/L, patients in different trajectory groups exhibited similar outcomes." (PMID 39101009, 2024). "Comparison of 28-day mortality rate and survival time in sepsis patients across different lactate, albumin, and lactate/albumin ratio levels." (PMID 38518050, 2024). "The role of serum albumin levels in sepsis is critical but not fully understood, particularly regarding the significance of albumin level changes over time." (PMID 39101009, 2024). "In paediatric patients with IPD who developed sepsis, the platelet, haemoglobin, PaO2, and albumin levels were significantly lower than those in patients without sepsis." (PMID 38898407, 2024). "In response to the recognized need for a deeper understanding of serum albumin level dynamics in sepsis patients, we have embarked on a retrospective study leveraging group trajectory models." (PMID 39101009, 2024). "DEX administration reduces C-reactive protein (CRP) and procalcitonin levels in patients with sepsis requiring mechanical ventilation, improves albumin levels, and alleviates inflammation." (PMID 39881865, 2024). "Clinicians must pay close attentionto the lactate/albumin ratio to refine the riskstratification of sepsis patients and adjust the treatmentstrategy in time to improve the prognosis ofpatients." (PMID 39139159, 2024). "Assessment of lactate, albumin, and lactate/albumin ratio in forecasting 28-day outcome in sepsis patients." (PMID 38518050, 2024). "Our study also explores the trajectories of serum albumin levels in sepsis patients above 30 g/L, a patient subset often overlooked in past research, resulting in a lack of guidelines for the use of albumin therapy in this group." (PMID 39101009, 2024). "An American study has also revealed consistent findings about serum albumin levels and sepsis severity." (PMID 39539863, 2024). "The ratio results clearly show that the inhibitory effect of spermidine on FA binding to albumin was greater in FAF albumin than in the serum albumin of healthy subjects and was also markedly higher than that in the serum albumin of patients with sepsis." (PMID 39273360, 2024). "Baseline characteristics of the sepsis patients with different serum albumin trajectory groups at admission." (PMID 39101009, 2024). "This study aimed to evaluate the predictive value of early serum lactate and albumin levels and the lactate/albumin (L/A) ratio for 28-day prognosis in patients with sepsis." (PMID 38518050, 2024). "This study underscores the predictive value of early serum lactate and albumin levels and the L/A ratio for 28-day prognosis in patients with sepsis, with the L/A ratio showing a superior predictive capability." (PMID 38518050, 2024). "Albumin has been recognized for its partial anti-inflammatory effects and its potential benefits for patients experiencing sepsis." (PMID 38826606, 2024). "At the same time, thisstudy also indicated that the lactate/albumin ratiocould be a useful prognostic factor for sepsis patientsregardless of the initial lactate, liver, and kidney functionlevels." (PMID 39139159, 2024). "In the present study, serum albumin level was negatively and significantly correlated with the severity of sepsis via the SOFA scoring system." (PMID 39539863, 2024). "Score included only preoperative information (age, respiratory distress, sepsis, American Society of Anesthesiologists physical status, albumin, and creatinine)." (PMID 39116449, 2024). "Previous studies have indicated that low serum albumin levels during the acute phase of sepsis serve as a robust predictor of septic shock." (PMID 38510084, 2024). "In sepsis management, the approach to glycocalyx protection includes colloid substitution, preferably albumin and fresh frozen plasma; catecholamine restriction; restrictive fluid therapy; corticosteroids; anticoagulants; glycemic control; and vitamin C." (PMID 39202020, 2024).
Sepsis (continued). "The findings of the current study are consistent with previous research, supporting serum albumin level as a viable and trustworthy biomarker for evaluating the severity of sepsis." (PMID 39539863, 2024). "A nationwide multicentre study of 3967 patients with sepsis admitted to the ICU revealed that a decrease in serum ALB concentration one week after admission was a strong predictor of mortality in younger adults." (PMID 38898407, 2024). "The inclusion of biochemical indicators such as AST, albumin, and total protein highlights the critical role of liver function, nutritional status, and overall metabolic state in sepsis prognosis." (PMID 39844844, 2024). "Lower serum albumin levels significantly contribute to the increased severity of sepsis through several interconnected mechanisms." (PMID 39539863, 2024). "This study supports the use of serum albumin as a simple and cost-effective biomarker for early identification of sepsis severity, particularly in resource-limited settings." (PMID 39539863, 2024). "As a second-line and adjunctive to crystalloids for fluid resuscitation in hypovolemic shock, sepsis and septic shock, albumin clinical use is supported with a low to moderate quality of evidence." (PMID 38797509, 2024). "Specifically, this means that higher serum albumin levels were associated with lower SOFA scores, corresponding to less severe sepsis." (PMID 39539863, 2024). "C-reactive protein (CRP) and serum albumin have been shown to have utility in predicting outcomes in patients with sepsis including those with BSI." (PMID 39252713, 2024). "Our research showed that there was a close correlation between the BAR, a combined indicator of BUN and ALB, and the prognosis of TB patients complicated by sepsis." (PMID 39013924, 2024). "The results demonstrated that Mrp 8/14 combined with albumin had higher accuracy in screening the prognosis of patients with ARDS induced by sepsis (AUC 0.810, 95% CI [0.733–0.887], P = 0.000)." (PMID 39686985, 2024). "Albumin leakage in patients with sepsis during acute disease progression, along with early intensive therapeutic interventions (e.g., albumin therapy), prior to testing the albumin levels." (PMID 39058855, 2024). "The study revealed that early serum lactate, albumin, and the L/A have predictive values for 28-day prognosis in patients with sepsis." (PMID 38518050, 2024). "In conclusion, the structural and binding property differences of albumin in septic patients compared with healthy subjects underscore the complex biochemical changes that occur during sepsis." (PMID 39273360, 2024). "The results of this part of the research suggest that albumin infusions play a significant role in the management of ICU patients with sepsis, but the therapy is merely one means of controlling the variation of albumin levels within the patient’s body." (PMID 39101009, 2024). "The aim of this study was to examine the prognostic significance of serum albumin-to-creatinine ratio (ACR) in critically ill patients with sepsis." (PMID 39364026, 2024). "Many composite indicators using serum albumin are widely used in patients with sepsis and show higher predictive power than using parameters alone." (PMID 38898431, 2024). "A higher level of inflammation is suggested by a lower serum ALB level, especially in the setting of severe sepsis or septic shock." (PMID 39114290, 2024). "The study highlighted the interplay between inflammatory response serum sPLA2 activity and albumin’s fatty acid (FA) and lipid binding activity in the context of sepsis." (PMID 39273360, 2024). "In the present study, serum albumin level was noted as a reliable predictor of sepsis severity in ICU patients." (PMID 39539863, 2024). "In our study, ozone exposure lowered the ALT, AST, and bilirubin levels, while increasing albumin levels in sepsis-induced liver damage." (PMID 39336593, 2024).
Sepsis (continued). "The laboratory indices revealed significant recovery in the levels of CRP (p < 0.001), PCT (p = 0.005), PT (p = 0.014), Fib (p < 0.001), and ALB (p = 0.037) were significantly recovered from S0 to S3 and S7 in patients with sepsis." (PMID 39060743, 2024). "Our research rigorously evaluates the predictive capability of the leukocyte-to-albumin ratio (LAR) for acute kidney injury (AKI) in patients with sepsis." (PMID 38898431, 2024). "In this present study, we have acquired significant information regarding the correlation of serum albumin levels with the severity of sepsis in ICU patients." (PMID 39539863, 2024). "The introduction of novel markers, such as the lactate/albumin (L/A) ratio, serves as a prognostic indicator in critical care settings, particularly for patients with sepsis." (PMID 39205773, 2024). "This study utilized GBTM to investigate the diverse evolving trajectories of serum albumin levels in sepsis patients." (PMID 39101009, 2024). "Several studies have focused on finding good predictors associated with outcomes of sepsis, including cardiac index (CI), systolic vascular resistance index (SVRI), SSI, DSI, DBP, albumin, and lactate." (PMID 38693496, 2024). "Albumin levels acutely decrease during sepsis due to decreased liver synthesis as a response to inflammatory molecules as well as due to catabolism driven by the higher protein and energy requirements." (PMID 39272772, 2024). "On the other hand, patients with sepsis had higher serum albumin levels compared to those with septic shock (median, 3.5 g/dL, IQR, 30–38, range 18–45; mean rank difference, 0.78 g/dL; p ≤ 0.001; 95%CI [6.92, 8.61])." (PMID 38576552, 2024). "The study identified four albumin trajectory groups in sepsis patients, highlighting that those with persistently low levels had the worst outcomes, while those with increasing levels had the best." (PMID 39101009, 2024). "A Chinese study has also found that patients with lower serum albumin levels had more severe sepsis in comparison to patients with normal albumin levels." (PMID 39539863, 2024). "NLR and serum albumin were also highly predictive of in-hospital mortality in ICU sepsis patients, consistent with previous research." (PMID 38448999, 2024). "In this prospective study performed on resuscitated patients with sepsis and persistent tissue hypoperfusion, we showed that albumin infusion improved both peripheral and global tissue perfusion more than saline." (PMID 38326920, 2024). "Our study aimed to bridge this knowledge gap by selecting adult sepsis patients to delve deeper into the early predictive capabilities of the L/A ratio, serum lactate, and albumin concerning the 28-day prognosis." (PMID 38518050, 2024). "This study explores the correlation between serum albumin levels and sepsis outcomes in an intensive care unit (ICU) setting." (PMID 38826606, 2024). "The CD86%, neutrophil count, CRP/ALB, NLR, IL-6, IL-10, sIL-2R, CRP, and PCT levels were significantly higher, and the HLA-DR%, lymphocytes, PLT, and ALB levels were significantly lower in the sepsis group than in the non-sepsis group (all P<0.05)." (PMID 38603712, 2024). "Pearson's correlation and a simple linear regression model were used to assess the relationship between serum albumin levels and sepsis severity and the predictive capacity of serum albumin levels for sepsis severity respectively." (PMID 39539863, 2024). "The levels of AST, ALT, and total bilirubin seem higher in sepsis patients than in healthy controls, while creatinine and albumin seem lower in sepsis patients than in healthy controls." (PMID 39703776, 2024). "Patients with ICUAW were found to have a higher proportion of sepsis (61.8% vs. 11.9%, p < 0.001) and lower levels of albumin at ICU admission (23.7 ± 3.2 g/L vs. 30.0 ± 4.2 g/L, p < 0.001) than those without ICUAW." (PMID 39033122, 2024).